CD84 (CD84 molecule)
Diseases named in the same sentence as CD84 in open-access papers (continued):
Sharing a sentence is not in itself a finding about the gene and the disease.
viral infections (1 paper, 2024). "The cytoskeleton modulator intersectin 2 (ITSN2) has GEF activity and regulates expression of SLAM, CD84, and ICOSL to promote long-term B–T cell conjugate formation, as well as GC maintenance and memory against vaccination and viral infections." (PMID 39121196, 2024).
tumor (30 papers, 2016 to 2025). "TMEM144, enriched in monocytes and dendritic cells, is linked to M2 macrophage-driven tumour progression, and CD84 serves as a surface marker for myeloid-derived suppressor cells (MDSCs), facilitating their detection in cancer tissues." (PMID 40340807, 2025). "CD4+ Th-CXCL13 recruits tumor-associated B cells and induces plasma cell differentiation and immunoglobulin production through interleukin-21 (IL-21) secretion and CD84 interactions in TLSs." (PMID 35663939, 2022). "Deficiency of CD84 on stroma cells resulted in a reduction in tumor load in the BM and spleen, resulting in smaller spleen size as well as reduced IgG2b in the blood." (PMID 33465053, 2021). "Here, we report that CD84 is a highly expressed tumor-associated target in AML." (PMID 40198133, 2025). "Consistently, mice receiving CD84-knockdown cells exhibited reduced tumor burden and extended survival compared with control animals." (PMID 40198133, 2025). "In a mouse model of breast cancer, MDSCs features included several genes related to immunomodulation, such as arginase 2 and Cd84, and chemokine receptors (e.g., Ccr2 and Cxcr2), suggesting that MDSCs can be directed into tumor tissue by chemokines." (PMID 38609997, 2024). "We further verified that IACS-70654 reduced CD84+ BM neutrophils in 2208L tumor–bearing mice using flow cytometry." (PMID 39287984, 2024). "DIABLO (permutation test, p < 0.005) identified 15 transcripts in the CD20+ tumor cells (AOIs) to be positively associated with T-cell-rich MCLs, including IL7R, CD47, CD80, CD84 and NLRC5." (PMID 39001353, 2024). "Since the cytokines (Cxcl1 and Csf3) involved in immune cell recruitment and survival and Cd84 are elevated at day 7 in tumor-bearing mice, we tested if Ly6G+ mononuclear cells are present in MHV68-infected mice and are also a source of IL-6." (PMID 39338937, 2024). "The later study also identified CD84 as a specific cell surface marker for MDSC in tumor-bearing hosts." (PMID 35757733, 2022). "MM cells express undetectable to low levels of CD84, while cells in their microenvironment express high levels of this receptor in the presence of the tumor." (PMID 33465053, 2021). "While the elevation in the expression of CD84 on malignant cells was minimal, the upregulation of CD84 expression on cells derived from the tumor microenvironment compared with its expression on healthy donors was strongly enhanced." (PMID 33465053, 2021). "In vivo blocking of CD84 leads to reduced accumulation of MDSCs in the tumor microenvironment and to elevated activity of T cells through the control of essential functional pathways in MDSCs, leading to reduced tumor load." (PMID 33465053, 2021). "Since MDSCs play an important role in tumor maintenance, CD84 expression was determined on M-MDSCs (CD14+, CD11B+, HLA-DR–, CD15–) and granulocytic-MDSCs (G-MDSCs) (CD15+, CD11B+, HLA-DR–, CD14–) derived from BM patient samples." (PMID 33465053, 2021). "Blocking or knocking out CD84 in mice leads to a reduction in the levels of both M- and G-MDSCs, as well as a reduction in their immunosuppressive pathways, leading to an induced antitumor response by T cells and a reduction in tumor load." (PMID 33465053, 2021). "We therefore sought to determine whether the upregulated expression of CD84 on cells in the tumor microenvironment is modulated by MIF." (PMID 33465053, 2021). "Taken together, blocking CD84, can be used to reduce the expansion of MDSCs and, thus, decrease the immunosuppressive microenvironment, resulting in increased T cell activation, which in turn leads to a decrease in tumor load." (PMID 33465053, 2021). "The elevation of its expression suggests that CD84 might play a role in the cross talk between the tumor cells and their microenvironment." (PMID 33465053, 2021).
tumor (continued). "Thus, CD84 expressed on stroma cells in the tumor microenvironment regulates immunosuppression through MDSCs and functionality of T cells, which together result in the support of MM cell viability." (PMID 33465053, 2021). "Thus, CD84 deficiency in the environment of mice injected with MM results in a significant reduction in MDSC immunosuppression, resulting in a significant increase in T cell activity, and leading to a substantial reduction in tumor load." (PMID 33465053, 2021). "Key immune activation and tumor suppression genes including CD2, CD3, CD247 (CD3 zeta chain), CD48, CD84, CCL19, CXCL10, and SLAMF6 were consistently upregulated in the hot phenotype across all ancestries." (PMID 41387728, 2025). "The combination of CD84 and JAML cell surface receptors on MDSCs with CD11b/Gr1 staining detects the presence of MDSCs in mouse tumor tissues or in humans with CD11b/CD14 or CD15." (PMID 38609997, 2024). "The heterogeneities of myeloid-derived suppressor cells (MDSCs) have been documented, and specific markers such as CD84 and CD14 have been identified within tumor microenvironments." (PMID 38919617, 2024). "CD84 is a specific marker of MDSCs that is highly expressed in primary LUAD, thus indicating the immunosuppressive tumor microenvironment of tumor tissue." (PMID 37162299, 2023). "CD84 has been shown to be expressed by both PMN-MDSC and M-MDSC in patients with various cancers and in tumor-bearing mice." (PMID 35757733, 2022). "Downregulation of CD84 or its blocking reduce MDSC accumulation, resulting in elevated T cell activity and reduced tumor load." (PMID 33465053, 2021). "Blockade of CD84 with anti-CD84 monoclonal antibody (mAb) can greatly reduce PD1 expression on T cells and PD-L1 expression on tumor and myeloid cells, leading to reduced tumor load." (PMID 40344054, 2025). "We show that tumor cells have an increased expression of several markers (CD47, IL7R, NKG7, CD80, CD84, CSF1R, NLRC5/CITA, CD2 and IRF3) that may be involved in regulating the level of immune infiltration and the effect on tumor immunity." (PMID 39001353, 2024). "In the prospective cohort, two proteins; CD93 and CD84, displayed higher levels within the tumor samples when compared to non-tumors." (PMID 34885093, 2021). "At the same time, there was a large overlap between the genomes of PMN-MDSCs and M-MDSCs involved in immunosuppression, such as IL-1B, ARG-2, CD84, and WFDC17, and chemokine receptors, such as CCR2 and CXCR2, revealing that MDSCs could be migrated to the primary tumor by tumor-derived chemokines." (PMID 34527668, 2021).
cancer (10 papers, 2021 to 2025). A tumor composed of atypical neoplastic, often pleomorphic cells that invade other tissues. "In one of the most extensive review on the classification of M-MDSCs, CXCR1 and CD84 appeared as the two new phenotypic markers associated with their immunosuppressive activity that have been added for the classification of M-MDSCs in cancer." (PMID 37243699, 2023). "The six upregulated genes (FCGR3A, LPAR5, MATK, MNDA, TMEM144, and CD84) play key immunomodulatory roles in cancer progression and metastasis." (PMID 40340807, 2025). "CD84hi MDSCs exhibit T cell-suppressive capacity and increased reactive oxygen species (ROS) production, thus CD84 has also been identified as a marker of MDSCs in cancer of mice." (PMID 37350962, 2023). "In contrast, CD84 is present in a significant proportion of highly immunosuppressive M-MDSCs in the blood of cancer patients (between 60 and 95%), which is consistent with our observations in MS white matter lesions." (PMID 37243699, 2023). "Prior studies have shown that CD84 can upregulate PD-L1 expression in cancer." (PMID 36339710, 2022). "Specific surface markers proposed to identify neutrophil subsets in cancer include CD101 and CD177, which are associated with cancer regression, and CD117, PDL1, CD170, LOX1, CD84 and JAML, which are associated with T cell immunosuppression and cancer progression." (PMID 34674757, 2021). "Based on our findings that AIF-1 expression is positively correlated with the expression of CD28, CD84, CD86, and LAIRI in several cancer types, we hypothesize that further investigation into the potential association between AIF-1 and these immune regulators would be promising." (PMID 37014322, 2023). "Several immune-related genes exhibited marked variation: for example, CD84 and SMAD3 were abundant in T7 but almost undetectable in T15, whereas KANK1, often relevant in cancer prognosis, was highly expressed in T6 and T15 but absent in T7." (PMID 40764306, 2025). "Several immune-related genes showed pronounced variation: for example, CD84 and SMAD3 were abundant in T7 but nearly undetectable in T15, whereas KANK1, often relevant in cancer prognosis, was highly expressed in T6 and T15 but absent in T7." (PMID 40162205, 2025).
infection (9 papers, 2014 to 2025). The state of being infected such as from the introduction of a foreign agent such as serum, vaccine, antigenic substance or organism. "Taken together, these results suggest that CD84 deficiency dampens inflammation in the lung and contributes to prolonged survival after H37Rv infection." (PMID 35196822, 2022). "Our meta-analyses indicated that five out of the eight significantly identified genes (CD40, ICOS-L, SLAMF1, CD84, IL-21R) were downregulated continuously during infection." (PMID 37146079, 2023). "Previous investigations, however, have overlooked the need to examine the effect of infection status on CD84 expression levels." (PMID 35196822, 2022). "Surface reductions in CD84 and Ly108 were already observed at 24 h post-infection (hpi), and at 48 hpi for CD48 and CD229, becoming for all four receptors more pronounced at 72 hpi." (PMID 24626474, 2014). "However, experiments with CD84-deficient mice (in the absence of infection) have shown that B cell development is not affected by CD84 deficiency and that CD84-deficient B cells respond normally to antigen or mitogen stimulation in vitro and in vivo and do not show altered antibody production." (PMID 35196822, 2022). "During infection of IC-21 cells with MCMVΔm138, cell surface expression of ICOSL was maintained to levels similar to mock-infected cells, while the levels of CD84, a molecule targeted by the MCMV m154 protein, used as a control, markedly decreased." (PMID 33459589, 2021). "At different times (24 h, 48 h, and 72 h) after infection, cells were stained for the surface expression of CD48, CD84, CD229, and Ly108." (PMID 24626474, 2014). "Cd84 mRNA levels did not correlate with Jaml mRNA levels in wild-type mice after MHV68 infection, but these two MDSC markers did correlate in MHV68-infected K-RasLA1 mice." (PMID 39338937, 2024). "These coinhibitory molecules, however, unlike CD84, also function as inhibitory receptors in the absence of infection." (PMID 35196822, 2022). "The results showed no decrease in CD48, CD84, CD229, or Ly108 surface expression after infection of macrophages for 72 h with the UV-inactivated virus, indicating that SLAM downregulation could be attributed to specific MCMV genome-encoded products." (PMID 24626474, 2014).
CD84 also shares sentences with these, for which no sentence is quoted: multiple myeloma (3 papers); acute myeloid leukemia (2); Autoimmunity (2); infectious disease (2); Obesity (2); adenovirus infection (1); Burkitt lymphoma (1); depression (1); experimental autoimmune encephalomyelitis (1); gastrointestinal disease (1); ischemic stroke (1); Lipedema (1); lung adenocarcinoma (1); lung squamous cell carcinoma (1); lymphedema (1); lymphoproliferative disorders (1); melanoma (1); multiple sclerosis (1); nasopharyngeal carcinoma (1); neuroblastoma (1); Parkinsonism (1); psoriatic arthritis (1); respiratory disease (1); Thrombocytopenia (1).